SCD (stearoyl-CoA desaturase)
Diseases named in the same sentence as SCD in open-access papers (continued):
Sharing a sentence is not in itself a finding about the gene and the disease.
breast cancer (continued). "The current study addresses this apparent paradox by investigating the impact of estrogen on SCD-1 expression in estrogen receptor-α-positive breast carcinoma cell lines." (PMID 26022099, 2015). "It was found that the breast cancer cells were similarly sensitive to the cytostatic action of the small molecule SCD inhibitor." (PMID 19710915, 2009). "Treatment with mixed isomers, or more specifically 10-CLA, decreases either the activity or abundance of SCD-1 in a human breast cancer cells, human hepatocytes and murine adipocytes." (PMID 19761624, 2009). "Emodin inhibits breast cancer metastasis by reducing lipid synthesis through the downregulation of triglyceride synthesis-related genes, including Fas, glycerol-3-phosphate acyltransferase 1 (Gpat1), and stearoyl-CoA desaturase 1 (Scd1)." (PMID 40490812, 2025). "Additionally, SCD is also an upregulated gene in breast cancer tissue, as revealed by quantitative real-time PCR." (PMID 40002245, 2025). "This suggests that the dual inhibition of exogenous FA uptake and endogenous SCD-1-mediated de novo lipogenesis using CD36 and PI3K inhibitors might be a viable therapeutic approach in anti-HER2 resistant breast cancer with PTEN-loss." (PMID 39920872, 2025). "Accordingly, it is reported that FADS expression and activity determine ferroptosis sensitivity in gastric and ovarian cancer, whereas those of SCD sustain ferroptosis resistance in breast cancer, reinforcing the idea that PUFA intracellular availability is necessary for ferroptosis execution." (PMID 38926633, 2024). "Our previous study demonstrated that IC2, a derivative of ICT, could induce breast cancer cell apoptosis by Stearoyl-CoA desaturase 1 (SCD1) inhibition." (PMID 36770781, 2023). "Breast cancer cell-derived exosomes were used to deliver S100A4 siRNA that led to significantly reduced postoperative breast cancer metastasis, and exosomes loaded with SCD-1 siRNA significantly promoted anaplastic thyroid carcinoma cell apoptosis by enhancing its intracellular ROS level." (PMID 36119094, 2022). "Moreover, genetic and pharmacological ablation of SCD has been shown to significantly decrease proliferation and negatively impact survival of breast cancer cells." (PMID 29615666, 2018). "In the present study, we deepened our previous findings by focusing more in detail on the mechanisms involved in the SCD1-based control of breast cancer cell migration and demonstrated an unpredicted role for the other human SCD isoform, SCD5, in the maintenance of tumor cell survival." (PMID 29849946, 2018). "We observed that administration of Lovaza but not Raloxifene significantly reduced SCD-1 in postmenopausal women at increased risk of breast cancer based on high breast density." (PMID 29271901, 2017). "Finally, we found that high SCD expression is predictive of poor relapse-free survival in breast cancer." (PMID 27042297, 2016). "This study is the first to show that 17β-ED induces SCD-1 expression and the modulation of cellular lipid composition in estrogen-sensitive ER-α + ve breast carcinoma cells, and clearly demonstrates that SCD-1 expression and activity are required for estrogen-induced cell proliferation." (PMID 26022099, 2015). "Here we observed that the acute inhibition of SCD (∼95% reduction after 24 h treatment) with a specific small molecule inhibitor drastically reduced the rate of proliferation of a variety of human lung and breast cancer cell lines." (PMID 19710915, 2009). "However, SCD-1 inhibition by A939572 did not enhance the anti-proliferative effect of the PI3K inhibitors in anti-HER2 resistant breast cancer with PTEN-loss." (PMID 39920872, 2025). "Since lipid metabolic remodeling as an emerging mechanism participate in resistance to kinase inhibitors, we hypothesize that the inhibition of SCD-1 or CD36 might potentiate the effects of current PI3K-targeting agents in breast cancer with resistance to anti-HER2 drugs." (PMID 39920872, 2025).
breast cancer (continued). "Thus, ERα may contribute to resistance to ferroptosis by upregulating SCD-1 in ERα-positive breast cancer." (PMID 33292585, 2020). "However, no data are available in humans about the regulation of this enzyme by chemopreventive agents and it is not known how changes in SCD-1 activity relate to established biomarkers of breast cancer risk." (PMID 29271901, 2017). "Recently, SCD-1 has emerged as a potential therapeutic target since the inhibition of its activity or the silencing of its expression decreases proliferation in lung, colon, gastric, prostate, and breast cancer cell lines and tumor formation in xenograft models." (PMID 26022099, 2015). "Analysis of the METABRIC database revealed that genes related to fatty acid metabolism, such as ACLY, CPT1A, FASN and SCD, are most highly expressed in HER2-positive breast cancer." (PMID 40303293, 2025). "In an E2 receptor-positive breast cancer study, it was found that E2 stimulated SCD1 activity, as evidenced by the fact that SCD inhibition blocked cell proliferation." (PMID 40933871, 2025). "SCD expression shows significant correlations with clinical pathological features of breast cancer, particularly high expression in HER2+ breast cancer." (PMID 40923764, 2025). "Cancer cells are sensitive to sterols, and the expression of cholesterol and fatty acid biosynthesis genes (SREBF1/2, stearoyl-CoA desaturase (SCD), FASN) was inhibited by 25-HC in cancer cells, such as glioma, breast cancer, and prostate cancer cells." (PMID 36969840, 2023). "We found that SCD was upregulated in ductal breast carcinoma in situ and invasive ductal breast carcinoma (IDC—the most common type of breast cancer) samples, compared to normal tissue." (PMID 27042297, 2016). "Overall, these findings suggest that SCD-1 is a crucial player in the mitogenic effect of estrogen and supports the premise that SCD-1 is a therapeutic target in ERα + ve breast cancer." (PMID 26022099, 2015). "Furthermore, blocking PI3K signaling by alpelisib or inavolisib reduced SREBP1 and SCD-1 expression, suggesting that HER2/PI3K/AKT/mTOR signaling regulated the de novo lipogenesis machinery in HER2-positive breast cancer cells." (PMID 39920872, 2025). "Additionally, we noted the downregulation of SCD, coupled with the upregulation of PTGS1 and PTGSE, in tumor samples from some HER2‐positive breast cancer patients exhibiting secondary trastuzumab resistance compared to trastuzumab‐sensitive patients." (PMID 38460162, 2024). "In the CD4 low breast cancer cohort (n = 567), SCD expression data were not available for 59 patients (10.41%)." (PMID 39543650, 2024). "In the CD4 high breast cancer cohort (n = 533), SCD expression data were not available for 44 patients (8.26%)." (PMID 39543650, 2024). "Stearoyl-CoA desaturase-1 (SCD1), which catalyzed the conversion of stearoyl-CoA and palmitoyl-CoA into the monounsaturated fatty acids oleate and palmitoleate, contributed to β-catenin nuclear localization in MDA-MB-231 breast cancer cells to drive EMT." (PMID 33804114, 2021). "In breast cancer cells medroxyprogesterone acetate (MPA) treatment for 6 days increased glucose uptake and fatty acid synthase (FASN) and activation of stearoyl-CoA desaturase-1 (SCD-1)." (PMID 25866757, 2015). "Hypoxia-induced membrane remodeling releases PC, and high levels of PC containing unsaturated FAs as well as the enzyme SCD-1 were shown to be localized in cancerous areas of human breast carcinoma tissue rather than the stromal areas." (PMID 25605240, 2015).
breast cancer (continued). "It is important to note that estrogen represses SCD-1 in metabolic tissues but activates it in ER+ breast cancer cells, and that activation of SCD-1 via SREBP1 is central to estrogen-induced proliferation, thereby positioning the SREBP1–SCD1 axis as a therapeutic target for ER+ breast cancer." (PMID 40427160, 2025). "Finally, 6 upregulated DEGs (CST2, DRP2, CLEC5A, SCD, KIAA1211, DTL) and 6 downregulated DEGs (STAC2, BTNL9, CA4, CD300LG, GPIHBP1 and PIGR), were confirmed in a quantitative real time PCR comparison of breast cancer and paracancerous breast tissues from 8 clinical specimens." (PMID 31182966, 2019). "Unlike SCD1, the second human isoform of SCD, SCD5, seemed not to play a major role in the migratory ability of highly invasive breast cancer cells since its knockdown did not produce relevant variations in MDA-MB-231 cell migration." (PMID 29849946, 2018). "In order to verify that the antigrowth effect of the SCD chemical inhibitor was not cell type-specific, MCF-7 and MDA-MB-231 breast cancer cells, as well as in normal human WS-1 fibroblasts, were incubated with CVT-11127 for 24 h and cell proliferation was assessed by Crystal violet staining." (PMID 19710915, 2009).
steatosis (91 papers, 2009 to 2025). Increased lipid within the cytoplasm of cells. "Changes in the activity of stearoyl-CoA desaturase 1 (SCD1), delta-5 desaturase (D5D), delta-6 desaturase (D6D), and elongase have been linked to steatosis development." (PMID 40503664, 2025). "In vivo, SCD-1-/- mice feeding with a methionine-choline-deficient diet manifested decreased steatosis but markedly increased hepatocellular apoptosis and liver injury when compared to the SCD-1+/+ counterparts." (PMID 27104558, 2016). "Notably, SCD-1 deficient mice exhibit decreased steatosis, but increased hepatocellular damage during MCDD feeding." (PMID 26895034, 2016). "The study investigated the effects of IF, SCD probiotics and combination treatments on microvesicular steatosis, a form of hepatic fat deposition, in the aged‐related livers." (PMID 37897241, 2024). "The administration of IF, SCD Probiotics and combination treatments to aged rats led to a substantial decrease in hepatic microvesicular steatosis, suggesting their potential in mitigating age‐related liver changes." (PMID 37897241, 2024). "A beneficial effect of SCD-1 in the liver is supported by the fact that increased hepatocyte apoptosis, lipotoxicity and steatosis occur if SCD-1 is pharmacologically inhibited." (PMID 36678151, 2023). "Aramchol attenuates NASH in mouse models and decreases steatosis by downregulating the fatty acid synthetic enzyme stearoyl CoA desaturase 1 (SCD1) in hepatocytes." (PMID 34151243, 2021). "Increased SCD activity and a significant correlation between SCD and the severity of steatosis were found in NAFLD subjects." (PMID 31752380, 2019). "From their data we can obtain the SCD ratio for healthy (0.053), steatosis (0.076) or steatohepatitis (0.062) liver patients, which are within the same range of our findings." (PMID 29426919, 2018). "This increase in steatosis was found to correlate with hepatic stearoyl-CoA desaturase-1 (SCD-1) expression, an enzyme central to lipid metabolism." (PMID 26895034, 2016). "The genes we identified as steatosis-associated by the network analysis, such as ACOX1, SCD, PPARγ, CFD and CIDEC were re-discovered by the regression analysis." (PMID 19680557, 2009). "Physiologically, a downregulated SCD activity may prevent triglyceride accumulation in the liver particularly in the fetus, where an enhanced de novo lipogenesis may favor steatosis." (PMID 35360687, 2022). "In line with this speculation, SCD overexpression has been observed, in different cell types as well as in tamoxifen-induced hepatocyte steatosis, to significantly increase the rate of triglyceride synthesis." (PMID 30143015, 2018). "Aramchol, a partial inhibitor of hepatic stearoyl-CoA desaturase (SCD), reduced steatohepatitis and fibrosis in animal models and reduced steatosis in an early clinical trial of NASH15." (PMID 38693144, 2024). "Aramchol, an inhibitor of hepatic stearoyl-CoA desaturase (SCD1), can reduce steatosis, steatohepatitis and liver fibrosis in rodents." (PMID 37415199, 2023). "Inhibition of stearoyl-CoA desaturase (SCD) enzyme, the rate-limiting step in synthesizing monosaturated fatty acids, has also been shown to improve steatosis and insulin sensitivity." (PMID 35518541, 2022). "On the other hand, PUFAs prevent the liver from steatosis on a basis of SREBP-1c and lipogenic gene (e.g., FAS, ACC, and SCD-1) downregulation and then alleviate the hepatic inflammation by an amelioration of oxidative stress." (PMID 33294458, 2020). "In experimental models of steatosis in C. elegans and HFD-fed mice, caffeine promoted conversion from palmitic acid to palmitoleic acid by inducing the expression of SCD-1, resulting in changes in fatty acid composition and increased monounsaturated/saturated FFA ratios." (PMID 40002362, 2025).
steatosis (continued). "Our results suggest that TAM can induce hepatocyte steatosis in vitro and that the enhancement of fatty acid synthesis through the upregulations of SREBP-1c and its downstream target genes (FAS, ACC and SCD) may be the key mechanism of TAM-induced hepatocyte steatosis." (PMID 24603540, 2014). "However, there was also study showing that lack of SCD-1 activity would sensitize hepatocyte to SFA-induced apoptosis and render mice lack SCD-1 vulnerable to liver damage other than steatosis." (PMID 25105012, 2014).
lung carcinoma (81 papers, 2009 to 2025). "For instance, a high expression of fatty acid synthase and stearoyl CoA desaturase 1 (SCD1) is associated with relatively high risk of lung carcinoma and with poor patient prognosis." (PMID 33467111, 2021). "Clinically, high level of SCD expression is associated with poor prognosis in lung cancer patients." (PMID 36514170, 2022). "Interestingly, overexpression of SCD was associated with increased cancer cell proliferation, both in vitro for breast, prostate and lung cancer cells as well as in vivo." (PMID 27551323, 2016). "Lung cancer, in particular, exhibits insensitivity to the inhibitory effects of SCD, favoring enhanced activity of FADS2." (PMID 40535804, 2025). "Another study also demonstrated that the SCD inhibitor CVT-11127 inhibits SCD activity in human lung cancer cells, inhibiting cancer cell proliferation by blocking cell cycle progression and triggering programmed cell death." (PMID 41421797, 2025). "The modulation of lipid metabolism through interaction with fatty acid-binding proteins and suppression of stearoyl-CoA desaturase (SCD) expression in lung cancer, and induction of ferroptosis via STAT3 inhibition in hepatocellular carcinoma (HCC)." (PMID 40758729, 2025). "In lung cancer cells, inhibition of SCD activity by CVT-11127 impairs phosphorylation of EGFR, resulting in inactivation of downstream targets Akt and ERK, effectively controlling metabolism, proliferation, and survival of tumor cells." (PMID 41421797, 2025). "Recently, the high abundance of CYP4F11 in lung cancer tumours made it an attractive tool for prodrug activation targeting the stearoyl CoA desaturase (SCD)." (PMID 40858268, 2025). "Inhibition of SCD in A549 and H358 lung cancer cells further boosted the TGFβ-induced ferroptosis sensitivity." (PMID 39009641, 2024). "The analysis revealed that 1925 lung cancer and 719 adenocarcinoma patients with low expression of SCD had longer overall survival (OS), progression-free survival (PFS), and post-progression survival (PPS) than the patients with high expression of SCD." (PMID 36514170, 2022). "Combinatory use of SCD inhibitor reverts resistance of lung cancer stem cells to cisplatin and enhances sensitivity of hepatic cancer cells to sorafenib." (PMID 35370706, 2022). "Specifically, the median PFS in lung cancer and adenocarcinoma patients with low SCD expression was 27.14 and 41.4 months, respectively, and was 12.1 and 18.63 months, respectively, in patients with high SCD expression." (PMID 36514170, 2022). "CVT-11137 is a SCD inhibitor that promotes G1 cycle arrest and programmed cell death in lung cancer cells." (PMID 31936134, 2020). "It was also proved that in H460 lung cancer cells, the suppression of Stearoyl-CoA Desaturase (SCD) activity, impairs the ligand-induced phosphorylation of EGFR." (PMID 30876460, 2019). "We previously reported in lung cancer that CSCs maintenance is due to altered lipid metabolism and dependent upon Stearoyl-CoA-desaturase (SCD1)-mediated upregulation of YAP and TAZ." (PMID 30558661, 2018). "As expected, the growth inhibitory action of CVT-11127 was positively correlated with a significant inhibition of SCD activity in the lung cancer cells." (PMID 19710915, 2009). "To evaluate the potential use of newly developed SCD inhibitors as novel anticancer agents, we tested the potential growth inhibitory effect of CVT-11127, a novel small-molecule inhibitor of SCD activity, on several lung cancer cell lines." (PMID 19710915, 2009). "However, monounsaturated fatty acids (MUFAs) are synthesized by SCD, and induce a ferroptosis-resistant state in ovarian cancer and lung cancer cells by reducing the accumulation of cytotoxic lipid ROS in the biomembrane." (PMID 37051693, 2023). "However, fatty acid desaturase (FADS) can replace SCD in partially SCD1-dependent or SCD1-independent tumor cells such as liver and lung cancer cells." (PMID 37064872, 2023).